BRAF (B-Raf proto-oncogene, serine/threonine kinase)
Diseases named in the same sentence as BRAF in open-access papers (continued):
Sharing a sentence is not in itself a finding about the gene and the disease.
colon carcinoma (continued). "We found that BRAF and DPYD mutation rates in the high-risk group were significantly higher, indicating that the GIRlncPSig may help predict the BRAF and DPYD mutation in colon cancer patients." (PMID 34594379, 2021). "Collectively, our data put forward the possibility that molecular events associated with centrosome duplication, mitosis, transcription machinery and serine metabolism could play an important role in determining the responsiveness of BRAF mutant colon cancer cells to BRAF inhibition by PLX4032." (PMID 34201061, 2021). "Firstly, some molecular biomarkers such as microsatellite instability (MSI) and BRAF mutations that could affect the prognosis of stage II colon cancer were not included in our analysis, which might lead to a certain degree of bias." (PMID 33757442, 2021). "The involvement of increased regulation of AKT activity in drug resistance in BRAF mutant colon cancer was previously confirmed by higher basal levels of phospho-AKT in RKO cells intrinsically resistant to oxaliplatin in comparison with the responsive HCT116 colon cancer cells." (PMID 34639107, 2021). "Moreover, oral administration of ABC294640 supressed HT-29 xenografts growth in nude mice, which puts forward that targeting sphingosine kinase 2 by ABC294640 could provide a novel therapeutic opportunity for BRAF mutant colon cancer." (PMID 34639107, 2021). "Notably, although it is well acknowledged that dissimilar treatment strategies should be applied to MSS-type BRAF mutated colon cancer and MSI-type BRAF mutated colon cancer, no study has investigated tumor microenvironment among these subgroups yet." (PMID 34381786, 2021). "Importantly, we detected an upsurge in the expression levels and activity of c-Myc in both resistant cell lines after the PLX4032 challenge, which implies that c-Myc plays an important role in modulating vemurafenib resistance in BRAF mutant colon cancer cells." (PMID 34201061, 2021). "Thus, impairment in the regulation of S1P production accompanied by metabolic imbalance in ceramide salvage pathway could play a role in increased resistance to cytostatic effects of vemurafenib in BRAF mutant colon cancer cells." (PMID 34639107, 2021). "As to molecular tumor features, the significant survival advantage associated with a high immune response score was maintained in patients with MSS but not in those with MSI colon cancer, and in those with wild-type RAS/BRAF but not in those with mutated colon cancers." (PMID 33353162, 2020). "We observed that in HT-29 cell line, a combination treatment of TM and PLX4720 was able to induce a decrease in cell proliferation with respect to single treatments, suggesting that copper depletion might confer sensitivity to BRAF inhibition by PLX4720 in colon cancer cells bearing BRAFV600E." (PMID 31083627, 2019). "For example, BRAF harbors 10 non-silent mutations in TCGA colon cancer dataset." (PMID 30388102, 2018). "Other studies suggested that BRAF mutations confer a poorer prognosis on stage II to III colon cancers, but no conclusive prognostic significance for KRAS mutations could be reached among early and medium stage CRCs16–18." (PMID 29666387, 2018). "In addition, the current study did not consider the KRAS/NRAS/BRAF mutation statuses in colon cancer cells which are important for clinical outcomes and survival in cancer patients." (PMID 29732005, 2018). "Moreover, CDC37 was expressed at comparable levels, which were not affected by treatment with AUY922, in the colon cancer cell lines irrespective of their mutational status of BRAF." (PMID 27391062, 2016).
colon carcinoma (continued). "This suggests that colon cancer patients with BRAF (V600E) mutations, for whom there are currently no targeted treatment options available, might benefit from a combination therapy of BRAF and EGFR inhibitors." (PMID 26916442, 2016). "However, whether mutations in KRAS together with downstream factors BRAF, PIK3CA and NRAS impact prognosis is still unclear for stage II-III colon cancer." (PMID 27074743, 2016). "However CIMP-high tumors, regardless of BRAF mutation, are associated with reduced colon cancer mortality." (PMID 23965959, 2013). "Since the BRAF mutation status of these colon tumors was not reported, it is not possible to evaluate whether loss of MEIS1D27 was associated with BRAFp.V600E." (PMID 24244575, 2013). "Despite a number of descriptive reports on the prevalence of BRAF mutation and its correlation with clinicopathological characteristics, there has been no comprehensive comparison on the effect of BRAF mutation on patient survival in separate groups of right and left side colon cancers." (PMID 23056577, 2012). "However, the negative effect of BRAF mutation on right side colon cancer patient survival was persistently significant in multifactorial analysis (HR, 2.82; P = 0.002)." (PMID 23056577, 2012). "The availability of detailed and updated information on folate intake and tumor specimens within this cohort permitted a more comprehensive examination of the effect of folate intake on risk of developing CIMP-high and non-CIMP-high colon cancers as well as by BRAF mutational status." (PMID 21738611, 2011). "For example, in colon cancer, it has been observed that the clinical efficacy of combined EGFR/BRAF/MEK targeting correlated with increased ERK suppression." (PMID 41154654, 2025). "In this study, we demonstrate that MCs are enriched in BRAF mutant human CRC and mouse colon tumors, and secretory cells in human BRAF mutant CRC promote the migration of MCs in vitro." (PMID 41039118, 2025). "In a previous study that compared the tumor immune microenvironment of BRAF mutant (BrafV600ELgr5CreMin; BLM) and BRAF wildtype (Min) mouse colon tumors, CIBERSORT analysis of RNA-sequencing data revealed an enrichment for MCs in BRAF mutant tumors." (PMID 41039118, 2025). "In colon cancer, combinations of EGFR, BRAF inhibitors, chemotherapy, and immune therapy have been tested." (PMID 40977811, 2025). "When also MMR-status was considered (56% overlap between dMMR and BRAF-V600Emt), the differences became even more marked (RAS&BRAFwt/pMMR in 18% vs 41% vs 30%, p < 0.001), i.e., only a fraction of right colon tumours belong to a “treatment-sensitive group”." (PMID 40437037, 2025). "This was primarily because among the 53 studies included, only two RCT studies compared treatment outcomes for left and right colon cancer, and 13 RCT studies mentioned the RAS and BRAF status." (PMID 39048944, 2024). "Male gender, advanced age, colon tumors, early-stage tumors, NRAS mutant tumors, and BRAF wild-type tumors were identified as characteristics associated with CRC complicated by high-risk polyps." (PMID 38978992, 2024). "We demonstrate dynamic evolution of resistance to combined EGFR/BRAF/MEK inhibition in a pediatric patient with metastatic BRAF-V600E-mutant, mismatch repair-stable colon cancer." (PMID 39626159, 2024). "Combined BRAF, MEK, and EGFR inhibition can induce clinical responses in BRAF-V600E-mutant colon cancer, but rapid resistance often occurs." (PMID 39626159, 2024). "First, we considered the combination of a BRAF + EGFR inhibitor, which is an FDA-approved treatment for patients with BRAF mutant colon cancer." (PMID 39168097, 2024). "MCl-062 was effective against HCT116 human colon cancer cells, which harbor KRAS G13D, and was ineffective against HT29 cells harboring BRAF V600E." (PMID 37569406, 2023).
colon carcinoma (continued). "Here, we revealed DMS-low subtype was characterized as CIMP positive, mutant BRAF, MSI, and higher TMB, indicating this epigenotype of colon cancer identified by DMS had specific molecular alterations." (PMID 36276973, 2022). "A study carried in human colon cancer and embryonic kidney cell lines reported that RNF149 indirectly regulated cell differentiation by reducing BRAF, a kinase known for its pro-proliferation function." (PMID 35634494, 2022). "Our results showed that in BCPAP (BRAF V600E mutant), 8505C cells (BRAF V600E mutant), and HCT116 colon cancer cells (BRAF V600E mutant), endogenous BRAF V600E was localized not only in the cytoplasm, but also in the mitochondria." (PMID 35748101, 2022). "Across the cohort, six fusion gene rearrangements were identified in cancers of the colon (TPM-NTRK1), bile duct (FGFR2), thyroid (BRAF) and prostate (ETV4-CLTC, and TMPRSS2-ERG)." (PMID 36213130, 2022). "After screening for oncogenes or suppressor genes, KIT, KRAS, BRAF, and JAK2 were significantly higher in colon cancer ECs." (PMID 35755820, 2022). "In this study, we employed SW480 cells as the prototype of KRAS-driven colon cancer cells and RKO as the prototype of BRAF-driven colon cancer cells." (PMID 34136383, 2021). "When stratified by colonic location, BRAF-mut, CIMP+, and MSI-H status were more frequent in proximal colon cancer, compared with distal colon or rectal cancer (available online)." (PMID 34377935, 2021). "Studies have reported that BRAF/KRAS induces the activation of the MAPK/ERK signaling pathway, triggering colon cancer." (PMID 35003370, 2021). "As a consequence, it was shown that concurrent inhibition of BRAF and EGFR strongly reduces the growth of BRAF mutant colon cancer cells, both in vitro and in vivo." (PMID 33291749, 2020). "Since the CMS1–MSI-immune colon cancer subtype is also characterized by high MSI, high levels of BRAF mutations, and low levels KRAS mutations, we decided to explore whether CD68High tumors presented differences in HIF1A expression comparing MSI/MSS, and BRAF and KRAS wild-type versus mutated." (PMID 32231135, 2020). "For the treatment of potentially resectable colon cancer with RAS and BRAF wild-type status, LCRC with FOLFOXIRI ± cetuximab is recommended to patients, while FOLFOXIRI ± bevacizumab is recommended for RCC patients." (PMID 32161617, 2020). "Compared to other cancers with established biomarkers, such as PR, ER and HER-2 in breast cancer 12 and RAS, BRAF, MMR in colon cancer 13, PDAC lacks effective markers to assist in diagnosis, treatment and prognosis." (PMID 31892968, 2020). "For colon cancer, the main method to assess the outcome of patients is TNM, pathological grading systems, and some other markers such as KRAS status and BRAF status." (PMID 33304907, 2020). "At present, therapeutic planning for colon cancer requires the status of several established predictive biomarkers, including, RAS genes, BRAF, microsatellite instability." (PMID 32867793, 2020). "Treatment of colon-cancer challenged mice with rAF-IL12 had resulted in the downregulation of KRAS, BRAF, and MAPK1 expression in tumour while previous studies had reported that expression inhibition of these genes would improve patient survival." (PMID 32612457, 2020). "We found that VDR was highly expressed in chemotherapy, BRAF inhibitors and PI3K-mTOR inhibitors resistant colon cancer cells." (PMID 31596728, 2019). "Overall, our results showed a molecular sub-cluster of colon cancer cells with low CDX2 and VDR expression was sensitive to chemotherapy, BRAF inhibitors and PI3K-mTOR inhibitors treatment." (PMID 31596728, 2019). "For example, both VDR and CDX2 are highly expressed in chemotherapy, BRAF inhibitors and PI3K-mTOR inhibitors resistant colon cancer cells." (PMID 31596728, 2019).
colon carcinoma (continued). "Additionally, tumor molecular markers, such as microsatellite status, CpG island methylator phenotype (CIMP) status, BRAF mutations, and KRAS mutations as well as tumor immune infiltration have been linked to different recurrence risks and survival outcomes in patients with stage III colon cancer." (PMID 31619288, 2019). "We find that a molecular sub-cluster of colon cancer cells with low CDX2 and VDR expression is specifically sensitive to chemotherapy, BRAF inhibitors and PI3K-mTOR inhibitors treatment." (PMID 31596728, 2019). "The dual inhibition of BRAF and MEK was tested in patients with metastatic BRAFV600E colon cancers but showed little efficacy." (PMID 30185207, 2018). "In this retrospective study, we evaluated common hot spot gene mutations located downstream of EGFR signaling pathway, the potential prognostic value for KRAS, BRAF, PIK3CA and NRAS was assessed in 228 stage II-III colon cancer." (PMID 27074743, 2016). "The effect of BRAF and MEK inhibitors on cell viability and apoptosis in all three BRAFV600E colon cancer cell lines was examined next." (PMID 26802026, 2016). "The authors thank Bert Vogelstein (Howard Hughes Medical Institute, Johns Hopkins University) and Alberto Bardelli (University of Torino, Italy) for isogenic BRAF and KRAS colon cancer cell lines." (PMID 27351224, 2016). "HGUE-C-1 cells were also treated in culture with cetuximab, an antibody against the extracellular domain of EGFR, since this is a treatment used in advanced colon carcinoma patients and since HGUE-C-1 cells are wild type for KRAS and BRAF." (PMID 25885658, 2015). "We also confirm the synergistic activity of BRAF and EGFR inhibitors in BRAF-mutant colon cancer cell lines.The claim that EGFR and BRAF inhibitors are inactive in BRAF-mutant colon cancer lines appears unfounded however, as we observed a clear IC50 response." (PMID 26018524, 2015). "Recent evidences presented BRAF and KRAS oncogenes are involved in the TGF-β1 pathway which play an important role in induction and maintenance of EMT in colon carcinoma." (PMID 25277203, 2014). "Moreover, full exome sequencing of colorectal cancer samples by our group and collaborators revealed coincident GNAS and KRAS mutations in a small cohort of colon tumors, indicating GNAS mutations in colon cancers might also often be accompanied by mutations in KRAS and/or BRAF." (PMID 24498230, 2014). "Currently, only mutant KRAS, mutant BRAF, MSI and the Oncotype DX® Colon Cancer Assay are used in clinical practice." (PMID 24759962, 2013). "In a population-based study of 1315 patients with colon cancer, cigarette smokers had a higher incidence of MSI, CIMP, and BRAF mutant tumors." (PMID 22792460, 2012). "Herein, in order to improve cell response to BRAF inhibitor treatment, attenuation of the PIK3CAH1047 that co-exist with BRAFV600E in the relevant colon cancer cell lines was performed." (PMID 21738740, 2011). "Even more recently another study examined the effect of cetuximab on several colon cancer cell lines and found that PTEN null, PIK3CA mutant and Ras/BRAF mutants cell lines are resistant to cetuximab." (PMID 18700047, 2008).
colon carcinoma (continued). "In terms of the carcinogenic mechanism, colon tumors often displayed increased expression levels of HOX gene family 30, higher pathway activities of MAPK cascades 31, and constitutive activation of KRAS 32 and BRAF 33, 34, as compared to rectal tumors." (PMID 41323778, 2025). "MSI‐H or TMB‐H samples were significantly more abundant in the RAS/BRAF‐altered subset in both colon and rectal cancer: In the RAS/BRAF‐wt subset, 4.5% were MSI‐H and 7.8% TMB‐H, whereas in the RAS/BRAF‐altered subset 7.1% were MSI‐H and 10.6% TMB‐H in colon cancer (P < 0.001, Fisher's exact test)." (PMID 39865537, 2025). "Previous studies have shown a small or absent effect of BRAF on the prognosis of colon cancer treated with 5-fluoruracil-based chemotherapy." (PMID 38248103, 2024). "In colon cancer patients, pharmaceutical antineoplastic expenditure in 2019 included monoclonal anti-EGFR antibodies (53.78%), anti-angiogenic agents (31.92%), BRAF-MEK inhibitors (7.35%), the multi-kinase inhibitor regorafenib (1.19%), and cytotoxic agents (4.57%)." (PMID 37754495, 2023). "Hsp90 inhibition by AUY922 was shown to inhibit Akt phosphorylation in wild-type BRAF colon cancer cells but not in mutant BRAF colon cancer cells." (PMID 36012578, 2022). "The EGF receptor for example, is activated via a negative feedback loop in BRAF mutant colon cancer upon treatment with the BRAF inhibitor vemurafenib." (PMID 35365185, 2022). "Nevertheless, in most cases, these studies included both patients suffering from left- and right-sided colon cancer, regardless of RAS/BRAF mutational status." (PMID 36428606, 2022). "In the non-metastatic setting, testing for BRAF is recommended in patients with MSI-H colon cancer to identify those with Lynch syndrome; there is no current role in determining prognostication." (PMID 35323316, 2022). "OncoPanel was negative for BRAF:c.1799T>A Val600Glu, an observation that provides evidence against colon cancer of somatic origin." (PMID 36091175, 2022). "The tumor biopsy was also negative for BRAF Val600Glu, an observation that rules out somatic colon cancer." (PMID 36091175, 2022). "In case of progression, Docetaxel is added (except colon cancer), with or without Mitomycin C, and next cetuximab (except pancreatic and KRAS BRAF mutation cancers)." (PMID 36322580, 2022). "As colon cancers express high levels of activated EGFR, a combined blockade of EGFR and BRAF or even downstream MEK may work synergistically and could be a potential therapeutic opportunity in CRC." (PMID 34885128, 2021). "KRAS, NRAS, BRAF, HER2, and MSI must be evaluated in all patients with advanced colon cancer." (PMID 34541365, 2021). "In sporadic colon tumors with MSI, there is a high, but not complete, correlation between MLH1 methylation and BRAF V600E mutation." (PMID 33608032, 2021). "Taken together, our data suggested that AIM2 inhibits BRAF-mutant colon cancer growth in a caspase-1-dependent manner, which may provide evidence to understand the pathogenesis of CRC with BRAF-mutant, as well as new strategies for manipulation of CRC." (PMID 33842454, 2021). "Immunohistochemistry of participants A’s colon cancer biopsy demonstrated loss of protein expression of MLH1 and PMS2, indicative of MLH1 loss of function, and no BRAF V600 mutation was found in tumour DNA." (PMID 34711244, 2021). "Colon cancers without KRAS and BRAF mutations strongly respond to treatment with cetuximab and are rather resistant to the other three treatments." (PMID 34885128, 2021). "Our analysis revealed that BRAF mutant colon cancer did not harbor higher NHEJ1 expression compared to BRAF wild type tumors and three NHEJ pathway genes, XRCC5, PRKDC, and LIG4 are indeed lowly expressed in BRAF mutant tumors." (PMID 33195430, 2020). "For the BRAF and KRAS biomarkers and the other included prognostic features in the model, no predictive effect for adjuvant chemotherapy has yet been demonstrated in stage II colon cancer patients." (PMID 32458162, 2020).